TSPO (translocator protein)
Diseases named in the same sentence as TSPO in open-access papers (continued):
Sharing a sentence is not in itself a finding about the gene and the disease.
epilepsy (continued). "However, no systematic clinical studies have been conducted to directly evaluate the influence of ASMs on TSPO-PET signals in epilepsy." (PMID 40836311, 2025). "Epilepsy severity is another key factor influencing TSPO tracer uptake." (PMID 40836311, 2025). "We found that in tumor-free brain tissue from epilepsy patients, few cells expressed TSPO." (PMID 31963507, 2020). "Further, intrinsic factors to epilepsy such as partial volume effects due to hippocampal sclerosis may result in underestimation of TSPO expression in vivo." (PMID 23136853, 2012). "Therefore, in addition to FDG-PET, TSPO PET could be a useful neuroimaging approach for diagnosing early-onset child epilepsy." (PMID 33407581, 2021). "Therefore, it remains unclear whether there are differences in TSPO distribution between child and adult epilepsy, and few studies have investigated the usefulness of TSPO PET in child-onset epilepsies, including epileptic encephalopathies." (PMID 33407581, 2021). "However, as most of patients in this study showed refractory epilepsy, with obvious structural abnormality, frequent seizures, and long duration of epilepsy, the contribution of BZPs and sedative drugs to the TSPO uptake could be negligible." (PMID 33407581, 2021). "Furthermore, those studies did not exclude for comorbid epilepsy, which is associated with neuroinflammation and is associated with increased in vivo TSPO expression, included a wide age range and were limited to a few ROIs." (PMID 32076115, 2021). "One subject with ASD had a history of epilepsy and one subject with ASD was taking lorazepam which is a benzodiazepine with negligible binding to TSPO." (PMID 38615126, 2024). "TSPO has been shown to be upregulated in patients with TLE, neocortical epilepsy, and drug-resistant epilepsy, as well as in animal models." (PMID 34976232, 2021). "First, contralateral TSPO-PET signal increases are predictive for persisting epilepsy after successful treatment (i.e., temporary absence of solid tumor) of the primary tumor site." (PMID 39150564, 2024). "These pathways, while not specific to epilepsy, may help explain TSPO’s role in epileptic neuroinflammation and highlight its potential as a therapeutic target." (PMID 40836311, 2025). "While this could be due to low seizure frequency in this clinically-stable patients, one might also hypothesize that [11C]PK11195 lacked sensitivity to catch a modest TSPO increase in epilepsy." (PMID 34387719, 2021). "Therefore, TSPO brain images might not be conclusive for all individual epilepsy patients." (PMID 23136853, 2012). "Furthermore, due to the limited sample size, subgroup analyses based on epilepsy subtypes (e.g., temporal lobe epilepsy vs. extra‐temporal lobe epilepsy) or different pathological types of refractory epilepsy were not performed, as these may exhibit distinct TSPO uptake patterns." (PMID 39915832, 2025). "Another important limitation is the lack of cell-type specificity: TSPO is upregulated in various activated glial and immune cells, including microglia, astrocytes, and peripheral macrophages, and the relative contribution of these populations to the PET signal in epilepsy remains unclear." (PMID 40836311, 2025).
amyloid (20 papers, 2016 to 2026). "Given this background, we aimed in the present longitudinal Aβ/TSPO double tracer μPET study to explore the longitudinal association between amyloidosis and microglial response during aging of an amyloid mouse model in vivo." (PMID 30400912, 2018). "Despite the similar pattern of correlations across proteins, for a single protein, the correlations were more frequently observed with amyloid and TSPO PET (23 brain regions), and a smaller proportion with tau PET (14 brain regions)." (PMID 40289873, 2025). "The correlation of astrocyte TSPO tracer uptake between forebrain and hindbrain was also strongly reduced in presence of amyloidosis (Z = 0.83 in WT versus Z = 0.10 in AppNL−G−F)." (PMID 39238030, 2024). "Using analysis of brain regions with high (forebrain) and low (hindbrain) amyloidosis in AppNL−G−F mice compared to WT, microglia were identified as the dominant cellular contributor of TSPO-PET signals." (PMID 39238030, 2024). "CSF1R inhibition in amyloid mouse models also reduced ICCs of TSPO-PET compared to mice with amyloidosis and intact microglia, although depletion of microglia was incomplete (66%) after seven weeks of treatment." (PMID 39238030, 2024). "First, we applied typical target regions of amyloidosis and Braak-stages as predefined regions of interest to TSPO- and Aβ-PET analyses." (PMID 38263017, 2024). "These transgenic mice typically start expressing β-amyloid plaques at about 5–6 months of age, with a close correlation to TSPO expression during the later life course." (PMID 36906584, 2023). "We also demonstrate that ATV:TREM2 increased microglial activity and glucose metabolism in an amyloid mouse model via TSPO-PET and FDG-PET imaging, respectively." (PMID 36635496, 2023). "In this longitudinal study, we investigated serial TSPO-PET imaging as a tool for monitoring of chronic immunomodulation in two distinct mouse models of amyloidosis." (PMID 34522221, 2021). "It is interestingto note that the functional DA changes observed here are present at an age when thehippocampus showed TSPO increases and amyloid accumulation." (PMID 34286270, 2021). "Changes in cortical binding were transformed to Z-scores relative to wt mice, and microglial activation relative to amyloidosis was defined as the Z-score difference (TSPO—Aβ)." (PMID 30400912, 2018). "Given the differences by tracer in μPET alterations as functions of age, we aimed to compare directly the longitudinal time courses of TSPO activity and amyloidosis." (PMID 30400912, 2018). "Together, these results suggest that microglia activation, as measured by TSPO μPET signal and sTREM2 measurement, increase with normal aging, and this increase is strongly augmented by amyloid pathology." (PMID 28197095, 2017). "TSPO-PET therefore enables in vivo tracking of treatment-associated neuroinflammatory responses during anti-Aβ immunotherapy and provides a non-invasive framework for evaluating combination strategies targeting amyloid pathology and immune regulation in AD." (PMID 42196607, 2026). "Thus, as a logical consequence, microglia cells showed lower interregional correlation of TSPO tracer uptake in presence of amyloid pathology, which explained the PET derived findings at the cellular level." (PMID 39238030, 2024). "Building upon the variably elevated microglial tracer uptake per cell, microglia showed a reduced correlation of the TSPO uptake between forebrain and hindbrain in presence of amyloidosis (Z = 1.33 in WT versus Z = 0.93 in AppNL−G−F) and thus reduced forebrain-hindbrain synchronicity." (PMID 39238030, 2024). "We note that diphtheria toxin or receptor-based strategies could remove microglia in amyloid mouse models more effectively, which would allow studying the cellular specificity of TSPO-PET synchronization in AD mouse models in more detail." (PMID 39238030, 2024).
amyloid (continued). "Moreover, an association between translocator protein and amyloid PET binding was reported at the very early stages of amyloid pathology in asymptomatic elders." (PMID 34322007, 2021). "Furthermore, ceiling effects are unlikely as far higher magnitudes of TSPO activation and amyloidosis can be detected with these tracers in other circumstances." (PMID 30400912, 2018). "We present the first study employing post mortem assessment of sTREM2 and Aβ in conjunction with dual-tracer small animal μPET for TSPO and Aβ, aiming to reveal the spatial and temporal relation between microglial activation and amyloidosis during the life-course of a mouse AD model." (PMID 28197095, 2017). "Thus, the strength of the functional links between TSPO (i.e., the inflammatory reaction) and the presence of amyloid deposits may depend both on the area under consideration and on the progress of the pathology." (PMID 32839410, 2020). "Dual tracer μPET imaging of Aβ and TSPO was recently established in the transgenic PS2APP mouse model, a strain that is known for a strong inflammatory component besides the remarkable age-dependent amyloidosis; the dual tracer approach revealed associations of neuroinflammation and amyloidosis." (PMID 28197095, 2017). "Moreover standardized differences of TSPO-PET and sTREM2 reached or even exceeded the level of fibrillar Aβ deposition and total Aβ, underlining the parallel increase of neuroinflammation and amyloidosis with age in the studied mouse model." (PMID 28197095, 2017). "Biologically, women are predisposed to higher levels of neuroinflammatory markers than men, which has been shown using TSPO-PET across studies in healthy adults and animal models of amyloidosis." (PMID 39794447, 2025). "Using TSPO-PET imaging of mice with depleted microglia and scRadiotracing in an amyloid model, we provide first evidence that a microglia connectome can be assessed in the mouse brain." (PMID 39238030, 2024). "Moreover, translocator protein (TSPO)-PET and FDG-PET imaging have demonstrated that TREM2 activation enhances microglial activity and glucose metabolism in amyloid mouse models." (PMID 40247363, 2025). "Finally, we analyzed TSPO expression in a scRNA dataset of APP23 and WT mice and found enhanced TSPO in the cortex and the hippocampus but not in the cerebellum of aged mice with amyloidosis." (PMID 39238030, 2024).
amyotrophic lateral sclerosis (19 papers, 2014 to 2025). Amyotrophic lateral sclerosis (ALS) is a neurodegenerative disease characterized by progressive muscular paralysis reflecting degeneration of motor neurons in the primary motor cortex, corticospinal tracts, brainstem and spinal cord. "TSPO may be a critical diagnostic target for all stages of AD, PD, and amyotrophic lateral sclerosis (ALS)." (PMID 39325320, 2024). "In neurodegenerative disorders, such as AD, PD, MS, Huntington’s disease (HD), and amyotrophic lateral sclerosis (ALS), TSPO was found to be highly expressed at sites of injury and in microglia and astrocytes." (PMID 31288390, 2019). "For instance, while an abnormal signal was detected in the motor cortex of patients with amyotrophic lateral sclerosis using TSPO tracers, in the same patients, no signal was detected with a more cell-selective microglial purine receptor P2X7 tracer." (PMID 39013020, 2025).
ischemic stroke (18 papers, 2017 to 2023). A stroke disorder caused by obstruction of blood flow to the brain, due to thrombotic (local blood clot formation) or embolic (due to a blood clot or other material traveling from another site) event. "The translocator protein (TSPO) is known to be found in arterial plaques, which are a symptom of atherosclerosis and a contributory cause of ischemic stroke." (PMID 37443691, 2023). "It is known that TSPO is present in arterial plaques, which are a characteristic of atherosclerosis that can be a contributing cause for ischemic stroke." (PMID 32252470, 2020). "TSPO-tracers were also found to localize to magnetic resonance imaging (MRI)-identified ischemic lesions within ischemic stroke patients, further demonstrating the tracer’s feasibility to map inflammation after tissue damage." (PMID 37108685, 2023). "As a selective radioligand of TSPO it has been used to study the magnitude of inflammation after acute ischaemic stroke in patients but several methodological issues have limited the usefulness of this radioligand." (PMID 37193998, 2023). "Using the second generation TSPO tracer [11C]vinpocetine, Gulyás and colleagues measured the regional changes of TSPO in the brain of nine ischemic stroke patients up to 14 weeks after the insult." (PMID 37193998, 2023). "As described in previous studies, high TSPO expression was observed in the LPS-induced neuroinflammatory rat model 4 days after injection and was maximum 11 days following ischemic stroke." (PMID 34783879, 2021). "TSPO-PET uptake in the process of Wallerian degeneration was previously observed in ischemic stroke patients." (PMID 31960097, 2020). "This presents one reason why the therapeutic potential of targeting TSPO warrants further investigation in ischemic stroke." (PMID 32252470, 2020). "Here, we present the first head-to-head comparison of 2 second-generation TSPO PET tracers in a rodent model of ischemic stroke." (PMID 29976695, 2019). "The overexpression of TSPO might be due to the severe damage suffered by blood vessels during ischemic stroke, that results in the activation of endothelial cells during the acute and subacute phases of ischemic stroke." (PMID 37175644, 2023). "Due to the activation of microglia, the TSPO density is elevated after ischemic stroke." (PMID 34630278, 2021). "Furthermore, it has been demonstrated that using [11C] vinpocetine, a prospective radio ligand of TSPO, the regional changes of TSPO can be measured in the brain of ischemic stroke patients." (PMID 34630278, 2021). "The therapeutic potential of targeting TSPO requires further investigations in ischemic stroke." (PMID 28754131, 2017). "The purpose of our pilot study was to describe the activation of microglia by in vivo brain expression of TSPO using [11C]PBR28 PET imaging co-registered with MRI structural imaging in the subacute and chronic stages after ischaemic stroke." (PMID 37193998, 2023). "More recent studies have demonstrated the specificity of [18F]F-DPA towards TSPO and its usefulness in imaging glial activation in the APP-PS1/21 mouse model of AD and in a model of ischemic stroke." (PMID 34542805, 2022). "Accordingly, the aim of this study was to directly compare 2 promising second-generation TSPO tracers, 11C-DPA-713 and 18F-GE-180, for the first time at acute and chronic time points after ischemic stroke." (PMID 29976695, 2019). "In the present study, we demonstrate the relationship of microglial activation and AChE activity using TSPO and AChE targeting positron emission tomography (PET) radioligands, and manipulating respective activities with inhibitors, in the ischemic stroke rat model." (PMID 34072449, 2021). "The autoradiography results confirmed the selectivity and specificity of previously performed TSPO PET results, with no inhibition and significant reduction of radioactivity in flumazenil- and PK 11195-treated ischemic stroke rat brain slices, respectively." (PMID 34783879, 2021).
myocardial infarction (18 papers, 2015 to 2025). Gross necrosis of the myocardium, as a result of interruption of the blood supply to the area, as in coronary thrombosis. "Our procedure aimed at monitoring the inflammation response related to the abnormal TSPO expression in myocarditis, which causes acute myocardial infarction as well as necrosis." (PMID 29342117, 2018). "We implicate TSPO in the adverse remodeling associated with ischemia-reperfusion injury and myocardial infarction, both of which are major risk factors for arrhythmias." (PMID 25918579, 2015). "We previously reported the development of [18F]LW223, a quinoline-2-carboxamide bearing an R-configured side chain, which binds TSPO independently of the rs6971 human polymorphism and enables quantification of macrophage-driven inflammation in the course of myocardial infarction." (PMID 41497765, 2025). "Since increased TSPO expression occurs in various diseases such as inflammation or degeneration of the central nervous system, malignant tumors, and myocardial infarction, TSPO-specific ligands have received much attention." (PMID 38285284, 2024). "For example, immunohistostaining of mice one-week post-myocardial infarction indicated colocalization of TSPO to CD68+ microglia and cardiac monocytes within the brain cortex and infarcted myocardium respectively." (PMID 37108685, 2023). "In cardiovascular diseases such as myocardial infarction (MI) and artrial arrhythmia, TSPO could play the role of more than a diagnostic biomarker, as it can also serve as a therapeutic target." (PMID 38139248, 2023). "We and others have shown that the 18-kDa translocator protein (TSPO), previously known as the peripheral benzodiazepine receptor (PBR), likely plays a key role in cardiac injury during heart failure and myocardial infarction." (PMID 34149440, 2021). "TSPO-targeted imaging with the PET radiotracer 18F-GE180 also detected the increased inflammation after myocardial infarction both in mice and in humans." (PMID 34485416, 2021). "18F-LW223 has been shown to reversibly bind to its target, can be displaced by PK11195 (which indicates specificity to TSPO) while it also showed uptake consistent with macrophage infiltration after myocardial infarction in rats." (PMID 34485416, 2021). "We and other colleagues have reported that increased TSPO in the heart due to myocardial infarction begets increased neuronal TSPO expression." (PMID 34338808, 2021). "The possible cardioprotective effects of translocator protein (TSPO) modulation with its ligand 4′-Chlorodiazepam (4′-ClDzp) in isoprenaline (ISO)-induced rat myocardial infarction (MI) were evaluated, alone or in the presence of L-NAME." (PMID 33799869, 2021). "In three patients investigated after myocardial infarction, the frontal cortex was also positive on TSPO PET, similarly to the present finding in NHPs showing myocardial fibrosis." (PMID 33937770, 2021). "Using whole-body TSPO-targeted molecular imaging, we previously demonstrated that myocardial infarction imparts concomitant cardiac and neuroinflammation early after the insult, with recurrent neuroinflammation in chronic heart failure." (PMID 32125488, 2020). "Myocardial infarction evoked higher TSPO signal in the infarct region at 3 days and 7 days compared with sham (p < 0.001), with concurrent elevation in brain TSPO signal (+ 18%, p = 0.005)." (PMID 32125488, 2020). "We discuss evidence implicating TSPO in arrhythmogenesis in the settings of acute ischemia-reperfusion injury and myocardial infarction." (PMID 25918579, 2015). "TSPO responds to stress, and its expression is increased in pressure-overload induced heart failure (HF) in mice and in circulating monocytes and resident cardiac myocytes in post-myocardial infarction." (PMID 34149440, 2021). "PET imaging post-myocardial infarction (MI) revealed significantly increased TSPO signal in the infarcted myocardium, consistent with ex vivo macrophage markers." (PMID 41497765, 2025).
myocardial infarction (continued). "TSPO-PET has similarly been used as a marker of cardiac macrophage infiltration in previous studies of myocarditis, and myocardial infarction." (PMID 37108685, 2023). "In conclusion, whole-body TSPO PET imaging provides quantitative non-invasive indication of peripheral macrophages and central microglial activation after acute myocardial infarction, and altered mitochondrial function in chronic heart failure." (PMID 32125488, 2020). "Notably, the present study shows no reduction of TSPO PET signal or microglial content in the whole brain late after myocardial infarction with either early or delayed enalapril therapy." (PMID 32125488, 2020).